CD44 (CD44 molecule (IN blood group))
Diseases named in the same sentence as CD44 in open-access papers (continued):
Sharing a sentence is not in itself a finding about the gene and the disease.
cancer (continued). "It acts as a cell surface receptor of hyaluronicacid, and interferes with various biological processes suchas cell adhesion, cell migration and cancer metastasis.In addition, CD44 gene may increase the risk of tumorrecurrence in a variety of cancers." (PMID 31376327, 2020). "Similarly, ALK4L75A-Fc reduced cell surface levels of the cancer stem cell-associated marker CD44 in MDA-MB-231 and MDA-MB-468 cells treated with 2-DG or thapsigargin, while increasing expression of the CSC contraindicator CD24 in MDA-MB-231 cells." (PMID 33187540, 2020). "Single-nucleotide polymorphisms (SNPs) in CD44 gene may affect the protein expression, thereby influencing individuals’ susceptibility to cancer." (PMID 31682231, 2019). "Therefore, we conducted the first systematic meta-analysis to reveal the association of CD44 and its isoform CD44v6 and CD44v9 with the prognosis of advanced cancer patients by using multivariable survival data." (PMID 30788285, 2019). "CD44 expression is associated with cancer progression and metastasis." (PMID 31709180, 2019). "Moreover, CD44 gene rs187115 polymorphism appears to be genetic determinant of cancer susceptibility." (PMID 31682231, 2019). "In addition, MYC family members play crucial roles in stem cell biology, and MYC-dependent metabolic reprogramming is tightly related to regulation of CD44-variant-dependent redox-stress in cancer stem cells." (PMID 31088567, 2019). "In addition, our data suggested a cancer-associated expression of CD44, CD49b, CD87, CD95, and Ly-6C." (PMID 31428583, 2019). "Interestingly, the highest expression protein pattern of Gr-1+/CD44+ (Gr-1+ bright/CD44+ bright) within the CD11b+ subset was associated with early cancer disease in the blood of cisplatin treated 4T1 tumorous mice." (PMID 31881770, 2019). "CD44‐hyaluronan interactions have been associated with cancer invasion in the EMT." (PMID 30963578, 2019). "Interestingly, siBRCA1 treatment resulted in significant increase in the expression of cancer stem cell-associated markers including CD44, ALDH1A3, and OCT4, while leading to down-regulation of CD24 (p < 0.0001 for all pair-wise comparisons)." (PMID 31273285, 2019). "Interactions between matrix hyaluronan (HA), the major glycosaminoglycan component of extracellular matrix (ECM), and variant isoforms of CD44 (HA receptor) have been shown to be tightly linked to the development of aberrant signaling events in a variety of cancers." (PMID 31293964, 2019). "All these data suggested that CD44 rs187115 polymorphism may be a prognostic factor for different cancers." (PMID 31682231, 2019). "CD44 and its variants are implicated in probing the extracellular matrix and serve as tethers for cellular movement in a variety of cell types (e.g., immune cells and cancer cells), including under the shear stress of blood flow." (PMID 29925027, 2018). "xCT is stabilized by a variant form of CD44 which is associated with cancer stem cells." (PMID 30174791, 2018). "CD44 is closely associated with chemotherapeutic drug resistance in cancer cells." (PMID 30179299, 2018). "On the other hand, xCT is stabilized by interacting with the splice variant of CD44, one of surface maker molecules associated with cancer stem cells, causing enhanced glutathione level and an increased defense against reactive oxygen species in human gastrointestinal cancer cells." (PMID 29343855, 2018). "Normal colon cells express the standard form of CD44 (CD44s) whereas cancer cells may also express CD44 variants (CD44v) bearing supplementary domains underlying new oncogenic functions." (PMID 29416702, 2018). "CD44 is an adhesion molecule associated with lipid rafts and expressed in several cancers." (PMID 30719023, 2018).
cancer (continued). "In agreement, our real-time PCR analysis demonstrated that the mRNA level of oncogenic genes including cMyc, cyclin D1 and cancer stem cell associated markers, CD44, β-catenin and Axin-2 was all up-regulated in the spheres as compared to their parental counterparts." (PMID 30005681, 2018). "Cancer cells often express a large variety of CD44 variants, particularly in the advanced stages." (PMID 29872736, 2018). "Among CD44 variants, the isoform having exon 10 is known as a stemness factor in cancer." (PMID 29356399, 2018). "In summary, the wide array of structurally similar CD44 isoforms, associated with dense glycosylation and inadvertent lack of nomenclature consensus has posed a significant challenge for inferring on CD44 role in cancer." (PMID 29983670, 2018). "In contrast, the splice variant isoform of CD44 (CD44v) is only expressed in some epithelial cells during embryonic development, in lymphocytes during maturation and activation, and in several types of carcinoma." (PMID 29423071, 2018). "CD44+ phenotype cells within ovarian tumors correlate to the risk of cancer relapse and metastasis." (PMID 28417924, 2017). "Substantial evidence indicates that CD44 has been implicated in cancer invasion and metastasis." (PMID 28070170, 2017). "CD44 is a cancer stem cell marker associated with metastasis and stress resistance." (PMID 29138417, 2017). "Cancer stem-like cells of solid malignant tumors which highly express CD44v8-10, the variant isoform of CD44 generated by alternative splicing, has a resistance to redox stress by the robust production of glutathione mediated by ESRP1-CD44v-xCT (cystine/glutamate antiporter) axis." (PMID 28289330, 2017). "Finally, TβR1 contain a single cytoplasmic binding site for Cluster of differentiation 44 (CD44), suggesting a potential interaction between the TGFβ pathway and CD44, a cancer-associated glycoprotein previously reported as an OPN receptor." (PMID 28915803, 2017). "With respect to CD44, it is well known that such receptor varies in size due to glycosylation and alternatively spliced exon products (i.e., CD44v) and that these CD44 variants are often overexpressed in cancer cells and metastasis." (PMID 28769537, 2017). "Moreover, CD44 expressed on cancer-associated fibroblasts (CAFs) seems to support the stemness and resistance of neighbouring malignant cells." (PMID 29029509, 2017). "There are many studies to test the effects of several CD44 gene polymorphisms on cancer risk." (PMID 29445738, 2017). "It is well known that inherited and acquired changes in pre-mRNA splicing play a significant role in human disease development and many cancer-associated genes are regulated by alternative splicing, such as CD44, the Wilms' tumor gene WT1, BRCA1, MDM2, FGFR and kallikrein family members." (PMID 29156833, 2017). "Also, transcription factors including Snail, Slug, and Twist are activated with nuclear localization of β-catenin and increased expression of CD44, a stemness marker implicated in migration and metastasis of cancer cells." (PMID 27880942, 2017). "This may indicate CD44-mediated induction of EMT and may correlate with CD44 associated cancer stem cell initiation." (PMID 29137675, 2017). "CD44 is a cell surface glycoprotein that has been implicated in various cancers." (PMID 28910304, 2017). "Moreover, in a recent comparative analysis of signaling pathways between the CD44+/CD133+ colorectal CSCs and CD44−/CD133− cancer cells, Wnt pathway was shown to be highly associated with CD44+/CD133+ colorectal CSCs." (PMID 28356914, 2017). "Interestingly, CD109 shows a similar expression pattern to cancer stem cell marker CD44, and its overexpression was associated with better cancer-specific survival." (PMID 29207682, 2017). "In addition, epigenomics analysis of BCSCs derived from mammospheres reveals that JAK/STAT signaling is associated with the exhibition of CD44+/CD24− cancer stemness phonotype." (PMID 28445439, 2017).
cancer (continued). "We demonstrated a significant association of CD44 SNPs in modulation of cancer risk." (PMID 27521214, 2016). "Furthermore, CD44 has been recognized as a stem cell marker for several types of cancer and is strongly linked to metastatic spread." (PMID 27465541, 2016). "The conclusions from enrolled studies were controversial, and independent studies may not have sufficient statistical strength to precisely identify the effects of CD44 polymorphisms on overall cancer risk." (PMID 27738347, 2016). "However, in our study, we analyzed seven polymorphisms in CD44 and cancer risk, and the ethnicity comprised Asians and Caucasians." (PMID 27738347, 2016). "Although the expression of CD44 variant v6 constitutes a molecular hallmark of several human cancers, the exact mechanisms underlying its contribution to tumorigenesis remain unclear." (PMID 27409642, 2016). "Western blot analysis revealed up-regulation of pro-apoptotic protein BAX, along with the down-regulation of anti-apoptotic proteins (BCL-XL, Survivin), migration associated proteins (p-FAK, MMP-3) and cancer stem cell (CSC) markers (CD44, Oct-4), which was probably mediated by AKT/c-Jun pathway." (PMID 28036386, 2016). "Additionally, CD44 has been implicated in colorectal, prostate, breast, head and neck, and non-small-cell lung cancers." (PMID 27148537, 2016). "The resistant cells exhibited enhanced proliferative, clonogenic capacity with significant up-regulation of P-glycoprotein (ABCB1), c-Myc, survivin, β-catenin and a putative cancer-stem-like signature with increased expression of CD44, whereas the loss of E-cadherin signifies induced EMT phenotype." (PMID 27045798, 2016). "As SW13+ cells also express two markers associated with cancer stem cells (CD44 and cMET), they may have additional attributes which contribute to oncogenesis." (PMID 27188282, 2016). "Hence, we performed a meta-analysis of all eligible case-control studies to better interpret the associations between common SNPs of the CD44 gene (rs13347 C>T, rs10836347 C>T, rs11821102 G>A, rs713330 T>C, rs187115 T>C) and cancer risk." (PMID 27521214, 2016). "This limitation may have resulted in an insufficient power for identifying minor association between CD44 polymorphisms and cancer risk." (PMID 27738347, 2016). "CD44 polymorphisms have been previously associated with cancer risk." (PMID 28000766, 2016). "Recent studies have examined the association of specific single nucleotide polymorphisms (SNPs) in the CD44 gene with cancer risk but the significance of these findings remains unclear." (PMID 28000766, 2016). "Thus, our team performed a quantitative meta-analysis to allow for increasing statistical power and provide multiple lines of evidence for the relationship between CD44 polymorphisms and cancer risk." (PMID 27738347, 2016). "The subsequent CD44 downstream signaling is implicated in cancer cell invasion and growth." (PMID 25840418, 2015). "In this study, we report for the first time that TrkA is associated with CD44 in cancer cells." (PMID 25840418, 2015). "Functional single nucleotide polymorphisms (SNPs) of CD44 may modulate its gene functions and thus cancer risk." (PMID 26010608, 2015). "In addition, CD147 was found to regulate the lipid raft-associated CD44 function in cancer cell invasion." (PMID 26347743, 2015). "The expression of CD44 has been linked to cancer progression via metastases and drug resistance." (PMID 26448751, 2015). "The major cell-surface receptor for hyaluronan is CD44, a widely distributed type-I transmembrane glycoprotein that is implicated in a wide variety of biological processes, including cell adhesion and migration, as well as in inflammation and cancer." (PMID 26347743, 2015). "Besides CD44 expression on reactive mesothelial cells, CD44 was shown to be expressed on cancer associated fibroblasts (CAF), especially in hypoxic areas (like ascites)." (PMID 25991672, 2015).
cancer (continued). "This shRNA silences the expression of the selected CD44 variant in the target tissue cancer cells." (PMID 25999946, 2015). "Slightly weaker CD44 expression in high-grade cancers might indicate loss of its function in highly invasive disease." (PMID 25129125, 2015). "In addition, further studies have also stated that genetic variants in the CD44 gene were associated with cancer risk and prognosis." (PMID 26010608, 2015). "Because overexpression of CD44 is a hallmark of cancer angiogenesis and other types of tumor progression, HA is also used widely as a ligand in the fabrication of various nanotherapeutics targeted to cancer cells." (PMID 26078971, 2015). "Moreover, our data revealed that the expression patterns of variant CD44 differed between normal and cancer cells and that cancer cells were more likely to express CD44v isoforms than normal cells." (PMID 25909172, 2015). "Cytoplasmic positivity for CD44 may be associated with its cytoplasmic domain and it can be considered as an independent parameter during cancer progression, although in this case the association with Ki67 appears to be evident." (PMID 26504780, 2015). "CD44 is also known as a marker of cancer stem cells and its expression may cause therapeutic failure in many cancers." (PMID 25840418, 2015). "If one or several CD44 splice variants are found to be associated with cancer progression or treatment resistance, the possibility of targeting such a population will increase immensely, since these isoforms are not as abundantly expressed in the normal tissue as the standard CD44s molecule." (PMID 24122205, 2014). "Importantly, analysis of human CD44, a cancer-associated cell surface adhesion molecule, revealed that the edges and tips of GBM cell elongations contact the target pericyte." (PMID 25032689, 2014). "Previous studies have documented the impact of CD44 polymorphisms on human cancer susceptibility." (PMID 24699672, 2014). "CD44, a transmembrane glycoprotein that belongs to a family of cell adhesion molecules, is involved with the progression and metastasis of multiple types of cancer and has been associated with a poor prognosis in CRC patients." (PMID 24823486, 2014). "High CD44-expressing cells have heightened tumorigenicity, self-renewal in vivo, and give rise to functional as well as molecular heterogeneity: properties directly linked to chemotherapeutic-resistant, aggressive cancers." (PMID 24990559, 2014). "Significantly, the CD44+/CD24−/Low subpopulation revealed higher centrosome amplification compared to bulk SUM149PT cancer cells, suggesting that the higher degree of CIN observed in SUM149PT cancer cells was functionally linked to the genesis of CD44+/CD24−/Low CSCs harboring amplified centrosomes." (PMID 24970653, 2014). "The expression of CD44 is associated with cancer stem cell-like traits." (PMID 24999991, 2014). "Thus, in CD44 molecules in colon stem cancer cells, the variant exon 9 was considered an exceptionally important factor." (PMID 23800986, 2013). "We showed that expression of HIF-1alpha and its downstream target STC1 are upregulated in PGCCs or budding cells, and this expression is associated with several cancer stem cell markers such as CD44, OCT3/4, and Nanog and several EMT-inducing transcription factors, including Twist-2 and Snail." (PMID 24348907, 2013). "In particular, CD44s is abundantly expressed by both normal and cancer cells, whereas the variant CD44 isoforms (CD44v), that contain a variable number of exon insertions (v1–v10) at the proximal plasma membrane external region, are expressed mostly by cancer cells." (PMID 23533773, 2013).
cancer (continued). "Notably, clonogenicity in soft agar, a hallmark of cancer forming cells was also enhanced in CD44+CD24low+ cells compared to CD44+CD24neg in MDA-MB-231 and DT22." (PMID 23982961, 2013). "However, as a greater percentage of deaths in the chemotherapy resistant group were from stage III cancers, we cannot conclusively state that glycosylated Lewis y antigen and CD44 are associated with survival outcomes." (PMID 23468946, 2013). "In addition to vimentin and TGF-β, the transmembrane glycoprotein CD44 has been implicated in cancer cell migration and invasion." (PMID 23295955, 2013). "Hence, HA has been frequently utilized as a targeting moiety to detect CD44 in the diagnosis and treatment of specific cancers directly associated with CD44." (PMID 23547716, 2013). "In addition, the loss of different subunits of the SWI/SNF chromatin remodeling complex, which are mutated in numerous cancers, results in the loss of CD44 transcription." (PMID 23445749, 2013). "How these ID proteins maintain the cancer stem-cell phenotype is not known, but the response of GCSCs to TGF-β receptor inhibitors by reducing ID1, ID3 proteins and cell surface CD44 is very important as such markers appear to be functionally linked to the cancer-initiating phenotype of GCSCs." (PMID 23998913, 2013). "CD44 is known to have a complex expression patterns with ubiquitous expression and variant forms, and has been implicated in the aggressiveness and metastasis of a number of cancer types." (PMID 23226410, 2012). "CD44 is a multifunctional class I transmembrane glycoprotein generally acts as a specific receptor for hyaluronic acid, promoting migration in normal cells and highly expressed in almost every cancer cell in its standard or variant form." (PMID 22693526, 2012). "In addition to MMPs, the delocalization of cancer cells from the primary tumor is also caused by the decrement in the expression of cell adhesion proteins, for example, CD44, E-cadherins, integrin, and vimentin." (PMID 22174624, 2011). "CD44 is a cell surface protein linked to tumorigenesis in various cancers." (PMID 21915300, 2011). "CD44 is subject to extensive alternative splicing and different splice variants of CD44 have been shown to be involved in metastasis in a variety of different cancers and have been associated with poor patient outcome." (PMID 24212798, 2011). "In invasion of UC-associated carcinoma, adhesion between CD44 molecule and extracellular matrix might be more important than basement membrane disruption or the alteration of sialyl Lewis antigens." (PMID 21473743, 2011). "IMP1 expression is stimulated by Wnt/β-catenin signaling and has many regulatory targets, some of which are implicated in cancer: stabilization of c-myc and CD44 mRNAs, translational suppression of IGF2, and localization of β-actin mRNA to sites of actin polymerization." (PMID 20860831, 2010). "Similarly, genes coding for multiple cytokines and surface protein markers that are known to be associated with the basal phenotype, pluripotency, and cancer aggression, such as CD44, KIT, EGFR, and PROM1, were also significantly upregulated in the BORGHigh tumors." (PMID 39335212, 2024). "Moreover, CD44 is also found to be a component in some cancer‐associated signaling pathways." (PMID 38783892, 2024). "Therefore, profound understanding the underlying mechanisms of CD44 cleavage could develop new therapeutic approaches for cancer cell invasion and metastasis." (PMID 38736891, 2024). "This work systematically detected CD44 expression and mutation profile in pan-cancer, as a result, CD44 expression significantly increased within various cancers and associated with poor prognoses, indicating that CD44 has extensive carcinogenic roles in cancer." (PMID 38590654, 2024). "In studies of human cancers, CD44 is associated with STAT3, which may lead to STAT3 activation." (PMID 38247821, 2024). "Notably, some of these genes, like LMO7 and CD44, had been previously implicated in cancer." (PMID 39704173, 2024).